AP5B1 (adaptor related protein complex 5 subunit beta 1)
Description:
As part of AP-5, a probable fifth adaptor protein complex it may be involved in endosomal transport.
Synonyms: PP1030; AP-5; DKFZp761E198
Tractability: PROTAC: ubiquitination databases record sites on it.
Gene: Protein-coding gene on chromosome 11 (65,773,898 to 65,780,976, reverse strand). Ensembl gene ENSG00000254470.
Subcellular location (Human Protein Atlas): Nucleoplasm; Vesicles; Golgi apparatus
Gene Ontology:
Molecular function: protein binding
Biological process: endosomal transport; lysosome organization; vesicle-mediated transport
Cellular component: AP-type membrane coat adaptor complex; lysosomal membrane; AP-5 adaptor complex; late endosome; lysosome
Genetic constraint (gnomAD): Loss-of-function variants: 7 observed, 9.18 expected, observed/expected ratio (o/e) 0.76, 90% interval 0.43 to 1.42. That is too few expected variants to judge how well the gene tolerates losing a copy. Missense variants: 1,307 observed, 1,037 expected, observed/expected ratio (o/e) 1.26, 90% interval 1.2 to 1.32. Synonymous variants: 696 observed, 506.53 expected, observed/expected ratio (o/e) 1.37, 90% interval 1.29 to 1.46.
Homologues: Orthologues: chimpanzee AP5B1 (99% identical), macaque AP5B1 (97% identical), pig AP5B1 (86% identical), dog AP5B1 (85% identical), guinea pig AP5B1 (81% identical), mouse Ap5b1 (78% identical), rat Ap5b1 (77% identical), rabbit AP5B1 (73% identical), zebrafish ap5b1 (32% identical), tropical clawed frog ap5b1 (30% identical).
Diseases named in the same sentence as AP5B1 in open-access papers:
AP5B1 is named in the same sentence as 35 diseases in open-access papers, as found by Europe PMC text mining. Sharing a sentence is not in itself a finding about the gene and the disease. The quoted sentences say what the papers report.
hereditary spastic paraplegia (5 papers, 2011 to 2020). Hereditary spastic paraplegias (HSP) comprise a genetically and clinically heterogeneous group of neurodegenerative disorders characterized by progressive spasticity and hyperreflexia of the lower limbs. "The protein encoded by AP5B1 (adaptor-related protein complex 5 subunit beta 1) is involved with hereditary spastic paraplegia." (PMID 31272500, 2019).
asthma (3 papers, 2020 to 2025). "AP5B1 was identified as susceptibility loci for the combined eczema plus asthma phenotype, which might affect pulmonary function." (PMID 34809630, 2021).
allergic disease (2 papers, 2020 to 2025). An immune response that occurs following re-exposure to an innocuous antigen, and that requires the presence of existing antibodies against that antigen. "Most pleiotropic associations were exhibited by rs479844 (AP5B1, OVOL1 genes), which was associated with dermatological and allergic diseases, and rs4072037 (MUC1 gene), which was associated with magnesium levels and gastroenterological cancer." (PMID 32637184, 2020).
macular degeneration (2 papers, 2025 to 2026). Loss of vision in the central portion of the retina (macula), secondary to retinal degeneration. "We discovered genetic changes in three genes (AP5Z1, AP5M1, and AP5B1) that cause macular degeneration, affecting sharp central vision." (PMID 40081374, 2025). "Five unrelated patients from Europe and Iran were identified with a distinctive macular degeneration associated with bi-allelic variants in AP5Z1 (HGNC: 22197) and AP5B1 (HGNC: 25104), subunits of the vesicular fifth adaptor protein (AP-5) complex." (PMID 41830174, 2026).
atopic asthma (1 paper, 2018). An asthma that is characterized by symptoms that are triggered by an allergic reaction caused by inhaled allergens such as dust mite allergen, pet dander, pollen and mold. "AP5B1 (Adaptator protein complex 5), recently implicated in atopic asthma, T1 and T3 share a p.Leu211Phe pathogenic variant." (PMID 29510755, 2018).
diabetes (1 paper, 2016). "The previously identified UMOD locus showed genome-wide significant association with eGFRcrea among those with diabetes (rs12917707, P value=2.5 × 10−8), and six loci (NFKB1, UNCX, TSPAN9, AP5B1, SIPA1L3 and PTPRO) had nominally significant associations with eGFRcrea among those with diabetes." (PMID 26831199, 2016).
neurofibromatosis type 1 (1 paper, 2019). A clinically heterogeneous, neurocutaneous genetic disorder characterized by cafe-au-lait spots, iris Lisch nodules, axillary and inguinal freckling, and multiple neurofibromas. "Most significant enrichment was observed for NF1 (P = 0.000477, OR = 22.8), the gene causal for neurofibromatosis type 1 (NF1), followed by TRPM5, AP5B1, DNMT3L and ARFGEF1." (PMID 31175295, 2019).
osteoporosis (1 paper, 2020). A condition of reduced bone mass, with decreased cortical thickness and a decrease in the number and size of the trabeculae of cancellous bone (but normal chemical composition), resulting in increased fracture incidence. "Notably, the AP5B1 gene is associated with osteogenesis imperfecta type XII, which is an autosomal recessive form characterized by generalized osteoporosis, mild bone deformations, recurrent fractures, delayed teeth eruption, and white sclerae." (PMID 32637184, 2020).
psoriasis (1 paper, 2015). An autoimmune condition characterized by red, well-delineated plaques with silvery scales that are usually on the extensor surfaces and scalp. "In addition, four new susceptibility genes (C1orf141, GPR160, CCDC129 and AP5B1) with unknown functions in the pathogenesis of psoriasis were also identified, indicating that additional molecular mechanisms contribute to the risk of developing psoriasis." (PMID 25854761, 2015).
retinal disease (1 paper, 2025). "In summary, through a large multi-national collaborative effort involving multiple centers, we have identified pathogenic variants in the genes AP5Z1, AP5M1, and AP5B1 as an independent cause of a recessive form of retinal disease characterized by the progressive loss of macular photoreceptors." (PMID 40081374, 2025).
genetic disorders (2 papers, 2011 to 2025). "Conversely, AP5M1 and AP5B1 were not previously associated with any human hereditary disease." (PMID 40081374, 2025).
AP5B1 also shares sentences with these, for which no sentence is quoted: eczema (3 papers); infection (3); Anxiety (2); cancer (2); cognitive defects (2); viral infection (2); Airway obstruction (1); allergic rhinitis (1); Alzheimer disease (1); atopic dermatitis (1); atopic march (1); breast carcinoma (1); Granuloma (1); hay fever (1); ischemia (1); lysosomal storage disease (1); membranous nephropathy (1); ocular infection (1); parasitemia (1); Parkinsonism (1); primary effusion lymphoma (1); retinal degeneration (1); sarcoidosis (1); Spastic paraplegia (1).